ACE (angiotensin I converting enzyme)
Diseases named in the same sentence as ACE in open-access papers (continued):
Sharing a sentence is not in itself a finding about the gene and the disease.
Stroke (continued). "In present meta-analysis, we found that variant genotypes of ACE I/D polymorphism were associated with higher stroke risk, which was consistent with experimental findings." (PMID 23049705, 2012). "After adjustment, the use of statins (HR 0.79, 95% CI 0.69 to 0.90) and ACE inhibitor (HR 0.75, 95% CI 0.67 to 0.83) were associated with reduced risk of stroke." (PMID 22363662, 2012). "In a meta-analysis including 7,500 Han Chinese, the ACE DD genotype was associated with higher risk of stroke (OR[95%CI]=1.91 1.56-2.34)." (PMID 23049672, 2011). "In the case of ACE activity and homocysteine levels, a single estimate of biomarker - stroke risk was extracted from a single study, and previous meta-analysis, respectively, and then scaled in the same way." (PMID 20161734, 2010). "Additionally, low serum sodium levels and cessation of ACE inhibitors during the perioperative period increase stroke risk." (PMID 40809288, 2025). "Other genes associated with stroke and/or VaD risk include angiotensin-converting enzyme (ACE; only stroke), alpha-1 antichymotrypsin (ACT), glutamate-cysteine ligase modifier (GCLM), endothelial nitric oxide synthase (NOS3), and brain-derived neurotrophic factor (BDNF)." (PMID 39063013, 2024). "However, there was an increased risk of stroke outcomes for ACE inhibitors compared with diuretics; after accounting for multiple comparisons, this increased risk was no longer significant." (PMID 38048133, 2023). "This should include a comprehensive analysis of pharmaceutical agents used to regulate ventricular rate in atrial fibrillation, such as beta blockers, calcium channel blockers, digoxin, amiodarone, and ACE inhibitors, as these have been shown to reduce the risk of post-stroke aspiration pneumonia." (PMID 37107102, 2023). "Furthermore, there are inconsistencies in the inclusion of race in all guidelines and the reliance on US data without context for identifying short-term and long-term effects of ACE inhibitors such as angioedema or risk of stroke." (PMID 34508156, 2022). "Stroke and thrombosis might be caused by an overactive ACE/AngII/AT1R pathway because of its prothrombotic, pro-inflammatory, and vasoconstrictor effects, especially in venous circulation." (PMID 36419624, 2022). "However, ACE inhibitors/ARBs had 56 and 59% significantly higher risk of stroke compared to calcium channel blockers and diuretics respectively." (PMID 34508156, 2022). "For this reason therapies such as ACE inhibitors, angiotensin receptor antagonists or direct renin inhibitors, which are known to reduce microalbuminuria should be considered in order to reduce stroke risk." (PMID 34550097, 2021). "Inhibition of active ACE might reduce risk in humans and reduce the associated disability after stroke." (PMID 26730961, 2016). "PGx testing for ACE inhibitors and statins is less critical to risk of stroke recurrence, although it could reduce the burden of polypharmacy." (PMID 24351097, 2013). "In conclusion, this meta-analysis provided evidence of the association between the ACE I/D polymorphism and stroke risk, supporting the hypothesis that the ACE I/D polymorphism may be a low-penetrance susceptibility marker of stroke." (PMID 23049705, 2012). "Stratification analyses of the ACE I/D polymorphism on stroke risk." (PMID 23049705, 2012). "Stroke is a heterogenous disease and it is possible that ACE I/D polymorphism may play different roles in the differing subtypes of strokes." (PMID 23049705, 2012). "Furthermore, detailed gene-gene interaction and gene-environment interaction should also be considered in future studies, which should lead to better understanding of the association between the ACE I/D polymorphism and stroke risk." (PMID 23049705, 2012). "The same author examined the effect of ACE I/D polymorphism on stroke using the Gen-HAT data." (PMID 22135769, 2011). "ACE inhibitors are known to decrease the risk of having a stroke." (PMID 17302964, 2006).
Stroke (continued). "ACE inhibitors have been extensively studied in cardiovascular disease and have been shown in several clinical trials to decrease the risk of suffering a primary or secondary stroke." (PMID 17302964, 2006). "First-line ACE inhibitor caused more strokes compared to THZ." (PMID 15839739, 2005). "Some key genetic markers associated with stroke are brain-derived neurotrophic factor (BDNF), apolipoprotein E (ApoE, variant ε4), angiotensin-converting enzyme (ACE), and nitric oxide synthase 3 (NOS3)." (PMID 40142325, 2025). "Model coefficients for AIS and ICH can be found in S2 and S3 Tables and S1 and S2 Figs. Identified predictors common to all stroke types included age, population density, ACE inhibitors use, and calcium channel blockers use." (PMID 38820263, 2024). "ACE is a key player in aberrant RAS activity as evidenced by studies wherein pre-stroke ACE inhibition reduced ischemic stroke incidence and severity, and improved poststroke recovery (BI at discharge)." (PMID 38502340, 2024). "Angiotensin-converting enzyme (ACE) of the renin-angiotensin system plays an important role in stroke." (PMID 39575387, 2024). "In recent literature, candidate‐gene case‐control studies have identified multiple but consistent genetic associations with stroke, such as factor V Leiden, methylenetetrahydrofolate reductase (MTHFR), prothrombin, and angiotensin‐converting enzyme (ACE)." (PMID 39633841, 2024). "We did not establish an association of CYP2D6∗10, CYP2C9∗3, AGTR1 (1166A > C), ACE (I/D), CYP3A5∗3, and NPPA (2238T > C) gene polymorphisms with stroke susceptibility." (PMID 38298191, 2024). "Regarding stroke cases, polymorphisms in some genes such as MTHFR, eNOS, ACE, AGT, ApoE, PON1, PDE4D were associated with a higher risk of ischemic stroke." (PMID 38478535, 2024). "ACE inhibition increases the capillary density in stroke-prone spontaneously hypertensive rats and promotes angiogenesis in ischemic rabbit hindlimbs." (PMID 36759621, 2023). "Just under a third of patients in each group received ACE inhibitors pre‐stroke rising to over a third post‐stroke, and between 20.4% and 37.1% of patients in each group received diuretics pre‐stroke, increasing to between 24.4% and 39.8% post‐stroke." (PMID 35989512, 2022). "An ACE-I trial in stroke patients suggested that ACE-Is or angiotensin II receptor blockers in ICH patients result in less peri-haematomal oedema at 3 days, improve 3 month mortality and reduce rate of post-stroke pneumonia." (PMID 35098999, 2022). "Age, rurality and stroke were predictors of poor outcomes, while admission for arrhythmia, ACE inhibitor/angiotensin II receptor blocker use, high albumin and digoxin use were associated with better outcomes." (PMID 35641098, 2022). "Treatment with angiotensin converting enzyme (ACE) inhibitors in stroke patients can increase the level of substance P and reduce the incidence of pneumonia in patients with dysphagia." (PMID 35720359, 2022). "The pathogenesis of VaD is complex and is the result of a variety of cardiovascular or genetic risk factors associated with Apolipoprotein E (APOE), angiotensin I converting enzyme (ACE), paraoxonase 1 (PON1), or presenilin 1 (PSEN1) genes, or due to stroke." (PMID 34938197, 2021). "Risk factors associated with angioedema secondary to tPA administration have been documented in patients taking ACE inhibitors, as well as patients who develop strokes in the frontal lobe." (PMID 34436994, 2021). "The stroke rate was reduced by 25% in patients receiving the ACE inhibitor captopril in the CAPPP (CAPtopril Prevention Project) trial and this reduction reached 32% in the HOPE (Heart Outcome Prevention Evaluation) trial with the ACE inhibitor ramipril." (PMID 34201646, 2021). "After matching, there were no significant between-group differences for baseline variables, including BMI, β-blocker, CCB, ACE inhibitors, ARB, laboratory parameters associated with glucose or lipid metabolism, history of stroke, or smoking." (PMID 32183405, 2020).
Stroke (continued). "Regulation of the RAS by ACE inhibitors and ARBs has been reported to improve stroke outcome in hypertensive animals and reduce the severity of ischemic stroke in humans." (PMID 32922259, 2020). "CSF ACE levels can be elevated in neurosarcoidosis, demyelinating disease, vasculitis, stroke, and CNS malignant tumors, including astrocytoma, metastatic melanoma, medulloblastoma, and lymphoma, the latter being the case in our patient." (PMID 32957327, 2020). "Home medication (each of the following: anti-platelet, anticoagulation, statins, ACE-/AT1-inhibitor, beta-blocker and oral anti-diabetic) was also associated with recurrent stroke within the first year." (PMID 32584873, 2020). "Many stroke patients have comorbidities such as hypertension, have elevated blood pressure in the hospital after a stroke, and are prescribed antihypertensive medications such as beta-blockers, ACE inhibitors, and angiotensive II receptor blockers." (PMID 32802081, 2020). "When compared to control subjects, serum ACE levels were significantly increased in the large volume group within 24 h and 3 days after stroke by approximately 3.1-fold (P < 0.05) and 4.2-fold (P < 0.05), respectively." (PMID 29228591, 2017). "Compared with ACE inhibitors, low-dose diuretics were associated with reduced risks of CHF (RR 0.88, 95% CI 0.80–0.96), CV events (RR 0.94, 95% CI 0.89–1.00), and stroke (RR 0.86, 0.77–0.97)." (PMID 28725272, 2017). "A clinical study, the Perindopril pROtection aGainst REcurrent Stroke Study (PROGRESS), demonstrated that treatment with perindopril, a centrally active ACE inhibitor, reduces the risk of severe cognitive decline and stroke-related dementia." (PMID 28158298, 2017). "The final piece of the puzzle fell into place when the China Stroke Primary Prevention Trial (CSPPT) reported in 201546 a significant 25% reduction of stroke with folic acid versus placebo in hypertensive patients receiving the ACE inhibitor enalapril." (PMID 28721209, 2017). "Recent studies have shown that angiotensin-converting enzyme (ACE)of the renin–angiotensin system plays an important role in stroke." (PMID 26730961, 2016). "Between US$4 and US$7 million, the probability curve for a secondary prevention package for stroke consisting of aspirin, ACE-inhibitor and statin overlaps on the basic AMI package, making the choice less straight forward." (PMID 27524939, 2016). "About two-thirds of the patients were treated with any type of antihypertensive drugs, whereas the use of IPA, statins or ACE inhibitors was only documented in 30 % to 40 % of the subjects with stroke." (PMID 27141979, 2016). "57.0 % (MI), and 40.1 % (stroke) used statins, 65.1 % (MI), and 65.8 % (stroke) used any type of antihypertensives, and ACE inhibitors were prescribed in 49.7 % (MI), and 41.3 % (stroke)." (PMID 27141979, 2016). "We documented the under-prescribing of ASA, lipid lowering medications and ACE inhibitors and/or angiotensin receptor blockers to women with stroke, PVD and dyslipidemia." (PMID 24938405, 2014). "Meta-analysis of three candidate genes: MTHFR, ACE and APOE in Asian population, revealed a significant association of stroke with the MTHFR 677C>T polymorphism and APOE epsilon 4 alleles, in contrast to ACE gene insertion/deletion polymorphism." (PMID 22555977, 2012). "Stroke patients who were discharged alive were less likely to be prescribed aspirin, clopidogrel, Β-blockers, ACE inhibitors and statins at discharge." (PMID 22894647, 2012). "This encompassed age, gender, body mass index, use of acetylsalicylic acid, clopidogrel, beta blockers, calcium blockers, ACE inhibitors, ARBs, HMG-CoA reductase inhibitors, vascular risk factors, stroke history, stroke etiology, and mean IMT." (PMID 22675271, 2012). "A meta-analysis revealed that ARBs significantly reduced the incidence of stroke by just 8% when compared with angiotensin-converting enzyme (ACE) inhibitors." (PMID 22837724, 2012).
Stroke (continued). "It is the SE shared by drugs treating stroke, mainly ticlopidine and several angiotensin-converting enzyme (ACE) inhibitors." (PMID 22205936, 2011). "With respect to the ACE inhibitors, the experimental and clinical literature presents rather equivocal data on blood pressure related- or unrelated effects in stroke." (PMID 21901125, 2011). "The effects of AT1 receptor blocker, telmisartan, and the ACE inhibitor, ramipril, were tested head-to head and in combination on stroke prevention in hypertensive rats and on potential neuroprotection in acute cerebral ischemia in normotensive rats." (PMID 21901125, 2011). "This issue of Annals of Indian Academy of Neurology features a debate on the controversial topic, ‘ACE inhibitors will help in improving stroke outcome if given immediately after stroke’." (PMID 21085523, 2010). "For the four strongest positive gene-stroke associations– factor V Leiden, MTHFR, ACE and prothrombin - concordance between observed risk and that predicted from their associated biochemical changes was found." (PMID 20161734, 2010). "Except for ACE inhibitors in subjects with a history of stroke, all other odds ratios and confidence intervals were statistically significant and similar to the analyses including the entire population." (PMID 19493329, 2009). "BPLPRS studied the effect of ACE inhibitor, perindopril, combined with a diuretic, indapamide, on recurrent stroke in Chinese patients exclusively." (PMID 19843330, 2009). "Following the index stroke, 32.9% of patients filled at least one prescription for an ACE inhibitor, 16.9% beta blocker, 26.1% calcium channel blocker, 8.4% lipid lowering agent, 36.0% aspirin, 4.5% ticlopidine, 1.1% clopidogrel, and less than 1% dipyridamole." (PMID 16907982, 2006). "Similarly, variants of the angiotensin-converting enzyme (ACE) gene, known to affect blood pressure regulation and endothelial function, have shown opposing effects on stroke risk in European versus Asian populations." (PMID 40863347, 2025). "Additionally, while those with prior MI or stroke were more likely to be taking an ACE inhibitor, ARB, and/or MRA at baseline, use of these classes of medications did not substantially change over the study course." (PMID 38743423, 2024). "Thus, our present study sets the stage for a future study of this cohort of CD patients to elucidate the involvement of the ACE I/D genotypes in heart disease and stroke outcomes." (PMID 39591456, 2024). "Therefore, the association of CYP2D6∗10, CYP2C9∗3, AGTR1 (1166A > C), ACE (I/D), CYP3A5∗3, and NPPA (2238T > C) gene polymorphisms with stroke in hypertensive patients needs further studies." (PMID 38298191, 2024). "Top five important features of RF algorithm were socioeconomic factors (proportion of household with no high school education level and median household median income), time from cancer diagnosis to AFib onset, history of stroke, and concomitant use of ACE inhibitors or ARBs." (PMID 38499940, 2024). "Unfortunately, information on the hypertensive effect of 4-hydroxybenzoic acid is unavailable; however, ferulic acid (9.5 mg/kg) reduced blood pressure within 2 h after administration in stroke-prone spontaneously hypertensive rats, while a decrease in serum ACE activity was also observed." (PMID 38231711, 2023). "Furthermore, ACE inhibitors, DH CCBs, and diuretics appeared to be similarly effective in reducing cardiovascular deaths, stroke, and overall cardiovascular events." (PMID 32083689, 2020). "ACE inhibitors or ARBs are commonly given to stroke patients to control blood pressure." (PMID 32802081, 2020). "In our patients taking ACE inhibitors, ARBs, β-blockers, calcium channel blockers, or diuretics, ULT could still significantly lower the risk of stroke." (PMID 32175324, 2020). "Similarly, serum ACE concentrations increased in the small volume group within 24 h and 3 days after stroke by approximately 32% (P > 0.05) and 2.1-fold (P < 0.05), respectively." (PMID 29228591, 2017).
Stroke (continued). "Furthermore, some clinical evidence showed that serum ACE activity increased after acute ischemic stroke (AIS), while blockade of ACE was effective in preventing recurrent stroke, beyond the effect of lowering blood pressure." (PMID 29228591, 2017). "Furthermore, telmisartan, as an alternative therapy for cardiovascular disease patients who are intolerant to ACE inhibitors, was shown to induce a modest reduction in stroke incidence." (PMID 27761230, 2016). "E.g., the effect of statins on cardiovascular risk is not entirely mediated by cholesterol lowering, and the effect of ACE-inhibitors on stroke risk is not entirely explained by lowering of blood pressure." (PMID 26751377, 2016). "For example, in a cohort study of 4097 hypertensive patients, ACE-inhibitor users with the minor allele (T) of M235T (rs699) had higher risk of having MI and stroke compared to non-users with the common allele." (PMID 25278896, 2014). "Randomized studies have demonstrated the efficacy of lifestyle changes (e.g. smoking cessation, physical activity), and the use of medications such as aspirin, β-blockers, angiotensin-converting enzyme (ACE) inhibitors and statins to reduce death, reinfarction, or stroke in patients with CHD." (PMID 24188540, 2013). "There are several other potential mechanisms by which ACE-Is may provide benefit to stroke patients." (PMID 21085521, 2010). "The current review evaluates the role of ACE inhibitors in improving stroke outcomes." (PMID 21085521, 2010). "The first debate would be on whether the early use of angiotensin converting enzyme (ACE) inhibitors will help in improving the outcome of stroke." (PMID 21085520, 2010). "At the time of index stroke, 21.3% of patients had previously filled at least one prescription for an ACE inhibitor, 30.6% for a beta blocker, 23.4% a calcium channel blocker, 4.4% a lipid lowering agent (e.g., statin), 37.3% aspirin, and less than 1% each for dipyridamole or ticlopidine." (PMID 16907982, 2006). "Our results suggest that ACE-inhibitors may reduce the clinical severity of stroke, as measured by NIHSS score." (PMID 15949043, 2005). "Similarly, adenovirus delivery of ACE-targeted endothelial nitric oxide synthase (AdeNOS) to the carotid artery of stroke-prone hypersensitive rats significantly reduced blood pressure compared to untargeted virus, underscoring the biological efficacy of retargeting of viruses to ACE." (PMID 36735106, 2023). "Indeed, some drugs used in patients with cardiovascular disease, such as R-tPA and ACE inhibitors, may produce medication-induced angioedema, and, in turn, a stroke-like clinical picture may present in patients with HAE." (PMID 37569559, 2023). "Additionally, OLE treatment, in a rat model of stroke by occlusion of the middle cerebral artery, induces a decrease of cerebral edema and plasma fibrinogen, inhibition of angiotensin converting enzyme (ACE) activity, and an increase of the antioxidant enzymes SOD, GPX, and catalase in brain tissue." (PMID 37049607, 2023). "Furthermore, it has been reported that administration of ACE inhibitor captopril in Stroke-Prone Spontaneously Hypertensive Rat (SHRSP) exerted a tissue protective effect against stroke and created severe vascular lesions independently of the blood pressure lowering." (PMID 32922259, 2020). "A basic integrated package of aspirin, ACE-inhibitor, beta-blocker and streptokinase for AMI and a package of aspirin, statin and ACE-inhibitor for secondary prevention of stroke are the next two interventions that could be selected when more resources become available." (PMID 27524939, 2016). "The magnitudes of stroke risk observed for factor V Leiden, ACE, MTHFR and prothrombin, but not PAI-1, polymorphisms, are consistent with risks associated with equivalent changes in activated protein C resistance, ACE activity, homocysteine, prothrombin, and PAI-1 levels, respectively." (PMID 20161734, 2010).